TMEM268 (transmembrane protein 268)
Description:
Stabilizes cell surface expression of ITGAM and participates in the adhesion and migration of phagocytes during bacterial clearance.
Synonyms: C9orf91; DKFZp547P234; FLJ38045
Tractability: Antibody: UniProt places it where antibodies can reach, with high confidence; UniProt predicts a signal peptide or a membrane-spanning region; its Gene Ontology location is reachable by antibodies, with medium confidence; the Human Protein Atlas places it where antibodies can reach.
Gene: Protein-coding gene on chromosome 9 (114,611,206 to 114,646,422, forward strand). Ensembl gene ENSG00000157693.
Subcellular location: Cell membrane
Subcellular location (Human Protein Atlas): Cytosol; Plasma membrane
Gene Ontology:
Molecular function: protein binding
Cellular component: plasma membrane
Genetic constraint (gnomAD): Loss-of-function variants: 14 observed, 25.68 expected, observed/expected ratio (o/e) 0.55, 90% interval 0.36 to 0.85. The upper end of that interval is the gene's LOEUF score, 0.85, which puts it in group 3 of 6, group 1 being the genes least tolerant of losing a copy. Missense variants: 334 observed, 346.09 expected, observed/expected ratio (o/e) 0.97, 90% interval 0.88 to 1.06. Synonymous variants: 148 observed, 141.55 expected, observed/expected ratio (o/e) 1.05, 90% interval 0.91 to 1.2.
Homologues: Orthologues: chimpanzee TMEM268 (99% identical), macaque TMEM268 (98% identical), pig TMEM268 (92% identical), dog TMEM268 (90% identical), rabbit TMEM268 (88% identical), mouse Tmem268 (87% identical), rat Tmem268 (87% identical), guinea pig TMEM268 (86% identical), tropical clawed frog tmem268 (35% identical), Drosophila melanogaster CG18507 (20% identical), Caenorhabditis elegans C26B9.1 (14% identical).
Diseases named in the same sentence as TMEM268 in open-access papers:
TMEM268 is named in the same sentence as 5 diseases in open-access papers, as found by Europe PMC text mining. Sharing a sentence is not in itself a finding about the gene and the disease. The quoted sentences say what the papers report.
gastric cancer (3 papers, 2019 to 2022). A primary or metastatic malignant neoplasm involving the stomach. "TMEM268 deficiency in gastric cancer cells inhibits adhesion, decreases cell proliferation, regulates cytoskeleton remodeling, and finally depresses tumorigenesis and metastasis." (PMID 30361615, 2019). "In the present study, we demonstrate that TMEM268 deficiency in gastric cancer cells inhibits cell growth, adhesion, and causes cell cycle arrest." (PMID 30361615, 2019). "TMEM268-KO gastric cancer cells had reduced viability, proliferation rate and adhesion, all contributing to observed reduced tumorigenicity in a xenograft mouse model." (PMID 36612146, 2022). "The in vivo effects of TMEM268 were evaluated using a gastric cancer xenograft model established in BALB/C nude mice." (PMID 30361615, 2019). "To further prove the function of TMEM268 in gastric cancer cells, we knocked out TMEM268 in BGC823 cells." (PMID 30361615, 2019). "Xenograft tumor mouse model studies showed that TMEM268 deletion inhibits the tumorigenesis of BGC823 gastric cancer cells." (PMID 30361615, 2019). "Collectively, these data indicate that the inactivation of TMEM268 inhibits cell proliferation in gastric cancer cells." (PMID 30361615, 2019). "Recently, Transmembrane protein 268 (TMEM268) was reported to increase ITGB4 expression via enhancing its stability in gastric cancer cells." (PMID 30658712, 2019). "Moreover, the disruption of TMEM268-β4-integrin interaction in gastric cancer cells led to the displacement of plectin from the cytoplasmic tail of β4-integrins, leading to plectin binding to the actin cytoskeleton." (PMID 36612146, 2022). "Since TMEM268 inactivation impairs the adhesion and growth of gastric cancer cells, we therefore assessed whether TMEM268-deleted BGC823 cells lose the ability for distant metastasis." (PMID 30361615, 2019). "Further studies will focus on collaborating with the clinical laboratory to explore the relationship between TMEM268 levels and clinicopathological parameters of gastric cancer, which will offer evidence for estimating the possibility of TMEM268 as a potential target to prevent/treat gastric cancer." (PMID 30361615, 2019).
Sepsis (1 paper, 2024). Sepsis is defined as life-threatening organ dysfunction caused by a dysregulated host response to infection. "Our results reveal a positive regulatory role of TMEM268 in β2 integrin-associated anti-infectious immune responses and signify the potential value of targeting the TMEM268-CD11b signaling axis for the maintenance of immune homeostasis and immunotherapy for sepsis and related immune disorders." (PMID 38730209, 2024). "Tmem268 knockout in mice aggravated cecal ligation and puncture-induced sepsis, as evidenced by higher bacterial burden in various tissues and organs, congestion, and apoptosis." (PMID 38730209, 2024).
infection (1 paper, 2024). The state of being infected such as from the introduction of a foreign agent such as serum, vaccine, antigenic substance or organism. "Moreover, Tmem268 deficiency in mice inhibited phagocyte adhesion and migration, thus decreasing phagocyte infiltration at the site of infection and complement-dependent phagocytosis." (PMID 38730209, 2024).
TMEM268 also shares sentences with these, for which no sentence is quoted: tumor (2 papers); immune disorders (1).